RAE1 (ribonucleic acid export 1)
Diseases named in the same sentence as RAE1 in open-access papers (continued):
Sharing a sentence is not in itself a finding about the gene and the disease.
infection (continued). "In vitro infection of NIH 3T3, UC1b and MC57G cells with PyV does not change their expression of Rae-1 protein, and only in primary mouse embryonic fibroblast (MEF) cultures was an increase in Rae-1 expression seen after PyV infection." (PMID 20523894, 2010). "However, unlike VSV-M or ORF6, the RAE1•NUP98•ORF10 complex retains RNA-binding capacity, indicating that ORF10 overrides RAE1’s native specificity and contributes its own RNA-binding selectivity to support the export of transcripts promoting infection." (PMID 41101500, 2025). "The absence of surface expression occurred despite efficient infection of these cells, activation of the PI3K pathway, and a strong induction of RAE-1 mRNA, suggesting a cell type-specific block in a post-transcriptional step of RAE-1 biogenesis that does not prevent PI3K activation." (PMID 21966273, 2011).
RAE1 also shares sentences with these, for which no sentence is quoted: breast adenocarcinoma (1 paper); breast invasive carcinoma (1); breast tumour (1); cervical squamous cell carcinoma (1); cholangiocarcinoma (1); colon adenocarcinoma (1); endocervical adenocarcinoma (1); esophageal carcinoma (1); gastrointestinal disease (1); HCMV infection (1); head and neck squamous cell carcinoma (1); Hyperkeratosis (1); lethal congenital contracture syndrome 1 (1); lung adenocarcinoma (1); lung squamous cell carcinoma (1); neuroblastoma (1); rectal adenocarcinoma (1); Rotavirus infection (1); stomach adenocarcinoma (1); thymoma (1); uterine corpus endometrial carcinoma (1).